FOXP3 (forkhead box P3)
Diseases named in the same sentence as FOXP3 in open-access papers (continued):
Sharing a sentence is not in itself a finding about the gene and the disease.
pulmonary TB (8 papers, 2012 to 2020). "Pulmonary tuberculosis is associated with increased FOXP3+ regulatory T cells at the site of active inflammation." (PMID 25969456, 2016). "In concordance with the studies in pulmonary TB patients, our study suggests that there is an enrichment of FOXP3+ T cells in PBMCs as well as colonic tissue of ITB patients even without concomitant pulmonary TB." (PMID 29489879, 2018). "CD4+FOXP3+ T regulatory cells (Tregs) have been reported to be increased in patients with pulmonary tuberculosis." (PMID 29489879, 2018). "FOXP3 has been noted to be increased in the peripheral blood and sites of infection in patients with pulmonary TB." (PMID 29489879, 2018). "Recently, many studies have also shown an increase in CD4+CD25+FOXP3+ T lymphocytes in the blood and at the site of active infection in pulmonary tuberculosis patients." (PMID 29489879, 2018). "It has been shown that the leading part in immune suppression at infiltrative, dissemination, and fibrosis-cavity pulmonary tuberculosis is played by natural regulatory CD4+CD25+Foxp3+-T lymphocytes." (PMID 22666578, 2012). "On the other hand, Th17/FoxP3 ratio positively correlated with greater values of total and nadir CD4 + T cell counts and with pulmonary TB." (PMID 31906962, 2020). "Comparing and analysing these results in the study showed that levels of CD4+CD25+/CD4+,CD4+CD25+Foxp3+/CD4+ and TGF-β1 in pulmonary TB were higher than those in recovered TB patients and healthy controls while IFN-γ were lower." (PMID 23755239, 2013). "In pulmonary tuberculosis patients, CD4+CD25+Foxp3+Treg and TGF- β1 increase, demonstrating that the immune status in these patients is low, and that the pathogen, M. tuberculosis, cannot be effectively eradicated." (PMID 23755239, 2013).
AIDS (7 papers, 2006 to 2025). A syndrome resulting from the acquired deficiency of cellular immunity caused by the human immunodeficiency virus (HIV). "Some studies found that Forkhead box-P3 (FOXP3, a master TF for regulating differentiation and suppressive functions of Treg cells) expression increased in AIDS patients and repressed HIV-1 transcription." (PMID 34072421, 2021). "Demethylation of the FOXP3 promoter was significantly higher in AIDS patients than in healthy ones, which led to the high FOXP3 expression and increased number of Treg cells in the gut mucosa." (PMID 34072421, 2021). "In this study, we detected both FoxP3+Tregs together with CMV in intestinal mucosal biopsies of patients with HIV/AIDS." (PMID 32891157, 2020). "Expansion of CD8+FOXP3+ T cells has been described during the acute infection of rhesus macaques as well as in AIDS patients." (PMID 22162758, 2011). "Because the pathogenesis of a number of retroviral-induced immunologic disorders such as HIV-1/AIDS and HTLV-I/HAM/TSP have been associated with dysregulation of Foxp3 expression, we also examined the role of Foxp3 in retroviral gene expression." (PMID 16652169, 2006). "In addition to GVHD, CD8+Foxp3+Tregs can be induced and expanded in other inflammatory conditions, such as cancers, AIDs, CVIs, and TCR transgenic adoptive transfer models in mice with therapeutic potential as mentioned in detail elsewhere." (PMID 41009359, 2025). "Moreover, the high incidence of AIDs in women correlates well with different effects of CD25+CD4+Foxp3+Tregs and CD8+Tregs in immunoregulation in both sexes." (PMID 41009359, 2025). "Moreover, Qa-1-deficient mice are more prone to develop AIDs, such as experimental autoimmune encephalomyelitis (EAE), an experimental model for a human AID called multiple sclerosis, due to the deficiency of Qa-1-restricted CD8+Foxp3+Tregs." (PMID 41009359, 2025). "In this study, we detected FoxP3 and PD-1 in intestinal mucosal biopsies of patients with HIV/AIDS both with and without concomitant CMV colitis." (PMID 32891157, 2020).
airway hyperresponsiveness (7 papers, 2012 to 2025). "Studies on TGF-β1 and AHR indicate the increased AHR is related to decreased expression of TGF-β1 and Foxp3 in the lung and TGF-β1 suppresses airway hyperresponsiveness in allergic airway disease." (PMID 22844430, 2012).
anaphylaxis (7 papers, 2013 to 2023). An acute hypersensitivity reaction that occurs from exposure to an allergen. "In addition, FoxP3+ Treg cells are reported to be associated with anaphylactic shock severity in both mice and human, indicating that the increase in FoxP3+ Treg cells in AA‐fed whey‐sensitized mice could contribute to the prevention of anaphylactic shock symptoms." (PMID 32031763, 2020). "Oral treatment with C. butyricum significantly ameliorated anaphylaxis symptoms and increased sIgA and FoxP3+Treg cells in the spleen from BLG-sensitized mice." (PMID 30828329, 2019). "In this study, we provided evidence that Foxp3+ Treg can exert a physiological control of hypothermia, a major systemic symptom of anaphylaxis." (PMID 23922690, 2013). "Constitutive Foxp3+ Treg can control the symptomatic phase of mast cell and IgE-dependent anaphylaxis in mice." (PMID 23922690, 2013). "We document that MHC class-II restricted CD4+CD25+Foxp3+ Treg play a protective role in IgE-mediated systemic anaphylaxis in mice." (PMID 23922690, 2013). "Supporting these findings, in previous works applying identical SLIT with D1ManPrup3 in a similar Pru p 3-induced anaphylaxis mouse model, higher levels of Foxp3 were observed in the tolerant group compared to desensitized animals, which also translated into higher IL-10 levels." (PMID 37334360, 2023). "Thus, evidence that Foxp3+ Treg can control the symptomatic effector phase of immediate-type hypersensitivity and attenuate anaphylaxis remains scarce." (PMID 23922690, 2013). "In particular, oral supplementation with B. coagulans 09.712 and L. plantarum 08.923 significantly ameliorates anaphylaxis symptoms and increases the population of CD4+ CD25+FoxP3+ T cells through mTORC inhibition, FoxP3 upregulation, and GATA-3 downregulation." (PMID 30828329, 2019). "Following 8 weeks of treatment, EPIT-treated mice showed significant protection against anaphylaxis accompanied by a significant increase of Foxp3+ Tregs, especially CD62L+ Tregs, which was not seen in the absence of LCs." (PMID 30233572, 2018). "To determine whether complete ablation of Foxp3+ Treg aggravates symptoms of anaphylaxis, we used DEREG mice that express the DT receptor under the control of the Foxp3 promoter." (PMID 23922690, 2013).
autism (7 papers, 2015 to 2023). Persistent deficits in social interaction and communication and interaction as well as a markedly restricted repertoire of activity and interest as well as repetitive patterns of behavior. "The reduction of Ki-67+FOXP3+ cells may cause a higher vulnerability for immune dysregulations in ASD subjects with autism." (PMID 33562037, 2021). "As such, a specific alteration of T clones in PBMCs of autism patients versus typically developing children had already been observed in previous studies: a reduction in Foxp3 (T reg) and an increase in STAT3 and ROR γ t (Th17), T-bet (Th1) and GATA-3 (Th2) were noted." (PMID 37588589, 2023). "Recently, we showed that children with autism have fewer FOXP3+ cells." (PMID 33562037, 2021). "To evaluate the therapeutic potential of 5-AIQ administration in the BTBR mouse model of autism, we first investigated the effect of 5-AIQ on the FOXP3-producing CXCR6+ cells in the spleen." (PMID 33671196, 2021). "We investigated the influence of 5-AIQ-treatment in BTBR T+ Itpr3tf/J (BTBR) mice as an autism model and used flow cytometry to assess the effect of 5-AIQ on FOXP3, Helios, GATA3, IL-9, IL-10 and IL-17A production by CXCR6+ and CD4+ T cells in the spleen." (PMID 33671196, 2021).
chronic hepatitis B (7 papers, 2011 to 2021). "Their frequency and function vary in patients with chronic hepatitis B. In this study, we investigated the balance between IL-17+ T cells and Foxp3+ regulatory T cells and illustrated their function in the aggravation of chronic hepatitis B (CHB)." (PMID 21851644, 2011). "Our study suggests that intrahepatic IL17+ T cells played an important role in the development of chronic hepatitis B and that an imbalance between IL-17+ and Foxp3+ T cells in the liver might lead to progression of disease." (PMID 21851644, 2011). "However, the molecular interplay of Foxp3 and the IL-23/IL-17 pathway in patients with chronic hepatitis B (CHB) remains unclear." (PMID 21489307, 2011). "Interestingly, IL-17 has been associated with the pathogenesis of chronic hepatitis B in humans; however, the relationship between Foxp3+ Tregs and the IL-23/IL-17 pathway (via Th17 cells) has not yet been investigated in HBV infected individuals." (PMID 21489307, 2011). "We analyzed two SNPs in the FOXP3 gene, rs2280883 and rs3761549, in 392 patients with HCC, 344 patients with chronic hepatitis B (CHB) and 372 matched healthy controls." (PMID 23759077, 2013).
chronic obstructive pulmonary disease (7 papers, 2018 to 2025). A chronic and progressive lung disorder characterized by the loss of elasticity of the bronchial tree and the air sacs, destruction of the air sacs wall, thickening of the bronchial wall, and mucous accumulation in the bronchial tree. "The imbalance of CD4+Foxp3+ T cell subsets is reportedly involved in abnormal inflammatory immune responses in patients with chronic obstructive pulmonary disease (COPD)." (PMID 30842769, 2019). "It has been revealed that CV reduces emphysema in chronic obstructive pulmonary disease (COPD) and increases the anti-inflammatory cytokines and expression of the genes forkhead box P3 (FOXP3) and interferon gamma (IFNγ) in a model of asthmatic mice." (PMID 40298523, 2025). "CD4+FOXP3+ regulatory T cells (Treg) have been shown to be increased in the pulmonary lymphocyte follicles of chronic obstructive pulmonary disease (COPD) patients." (PMID 36139385, 2022).
colon adenocarcinoma (7 papers, 2012 to 2025). "In conclusion, this study show accumulation of CCR4+CTLA-4hi Treg stably expressing FOXP3 in colon adenocarcinomas, and close contact between Treg and conventional CD4+ and CD8+ T cells." (PMID 22319577, 2012). "Since HPV infection is suspected to contribute to the emergence of other cancer types (Bladder Urothelial Carcinoma (BLCA), HNSC, Colon adenocarcinoma (COAD), Prostate Adenocarcinoma (PRAD)), an HPV-associated pan cancer analysis of IKZF3, FOXP3, and JAK3 was performed." (PMID 35719936, 2022). "In colon adenocarcinoma, WTAP and YTHDF1 stabilize forkhead box P3 (FOXP3) mRNA, which further binds to the SMARCE1 promoter for transcriptional activation." (PMID 41373022, 2025). "Further analysis has shown that WTAP mediated the stability of Forkhead Box P3 (FOXP3) in an m6A-dependent manner to promote SMARCE1 transcriptional activation and ultimately enhance glycolysis in colon adenocarcinoma." (PMID 37297015, 2023).
dysplasia (7 papers, 2016 to 2024). A usually neoplastic transformation of the cell, associated with altered architectural tissue patterns. "But importantly, immune-suppressor, CD4+CD25+Foxp3+ Treg cells, which showed a gradual increase with progression of dysplasia to carcinoma in situ in 4NQO cohort, is significantly reduced after NLGP treatment." (PMID 38585261, 2024). "We observed increases of CD4+ T-cells, Foxp3+ T-lymphocytes, CD68+ macrophages, and IL-4+ cells during the progression of dysplasia in OLK and a parallel decrease in the expression of the inflammatory cytokine IFN-γ." (PMID 28053372, 2016). "We performed immunohistochemical staining for HLA-I, PD-L1, γH2AX (DNA damage marker), and immune cell markers such as CD8, FOXP3, CD68, and CD163 (in surgically resected specimens from 17 SCRC patients with 12 adjacent normal mucosa (NM) and 9 UC patients with 18 dysplasia/CC tumors." (PMID 37686454, 2023).
encephalitis (7 papers, 2015 to 2023). An acute inflammatory process affecting the brain parenchyma. "Although the role of CD4+Foxp4+ Tregs in flavivirus encephalitis remains elusive, CCR5-dependent recruitment of CD4+Foxp3+ Tregs may play certain roles in the control of encephalitis progression caused by flavivirus infection." (PMID 27439902, 2016). "Because an increased number of CD4+CD25+Foxp3+ Treg cells is correlated with milder forms of encephalitis caused by flavivirus infection, this finding suggests that IFN-γ produced from CD4+ Th1 cells can affect the progression of JE without changing the number of CD4+CD25+Foxp3+ Treg cells." (PMID 26597582, 2015). "CCR5 is also a key mediator to recruit CD4+Foxp3+ Tregs known as regulatory CD4+ T cell subset to dampen exacerbated inflammation such as viral encephalitis." (PMID 27439902, 2016). "Our study on cell culture model is corroborated with above finding in which we reported decreased levels of IL-21 and FoxP3+ which suggests that FoxP3+ level was decreased due to decreased level of IL-21 suggesting IL-21 has a role in the homeostasis of Tregs in viral encephalitis." (PMID 36707891, 2023). "A putative correlation between CD4+Foxp3+ Treg levels and the outcome of infectious disease has been reported in WNV encephalitis because patients with symptomatic infection have lower CD4+Foxp3+ Treg frequencies throughout the infection compared to asymptomatic patients." (PMID 27439902, 2016). "Therefore, CCR5 is involved in the putative role of CD4+Foxp3+ Tregs in severe flavivirus-induced diseases, such as encephalitis and hemorrhagic fever." (PMID 27439902, 2016). "Presumably, CCR5-dependent recruitment of CD4+Foxp3+ Tregs may affect the progression of viral encephalitis via their regulatory function." (PMID 27439902, 2016). "Recent work implicates CD4+Foxp3+ Tregs in the control of neuroinflammation caused by WNV32, wherein peripheral expansion of Treg was associated with mild inflammation, but reduced Treg levels were associated with WNV encephalitis." (PMID 26626303, 2015). "Our results suggest that CCR5 regulates the progression of viral encephalitis via governing a timely and an appropriate CNS infiltration of CD4+Foxp3+ Tregs and ultimately promoting survival of hosts suffering severe neuroinflammation." (PMID 27439902, 2016). "Similarly, in our model of viral encephalitis, PSA induced both FoxP3+CD39+Tregs and also FoxP3−CD39+CD73+CD4+ and CD73+CD8+ regulatory T cells." (PMID 31089128, 2019).
injury (7 papers, 2010 to 2026). Damage inflicted on the body as the direct or indirect result of an external force, with or without disruption of structural continuity. "Decreased percentage of Foxp3+ regulatory T cells (Tregs) in the lungs results in overwhelming inflammation and delayed recovery of acute lung injury (ALI) caused by acute respiratory distress syndrome (ARDS)." (PMID 41656950, 2026). "Besides macrophages, CD4+CD25+Foxp3+ Tregs (regulatory T cells) play a critical role in resolving acute lung injury." (PMID 37292149, 2023). "Since CD4+CD25+Foxp3+ Tregs play crucial roles in the TGF-β mediated regulation of immune response in acute lung injury, we next analyzed the levels of CD4+CD25+Foxp3+ Tregs in the peripheral blood from sham, LPS-instilled, and LPS-instilled QD-treated mice." (PMID 37292149, 2023). "We observed that CD4+T/CD8+T in peripheral blood T cells of craniocerebral trauma rats were significantly higher than those of normal rats, and the ratio of CD4+CD25+Foxp3 (Foxp3)+Regulatory T cell (Treg) was significantly lower than that of normal rats and caused increased secondary inflammation." (PMID 35874774, 2022).
invasive carcinoma (7 papers, 2020 to 2024). A carcinoma that is not confined to the epithelium, and has spread to the surrounding stroma. "In HR-negative invasive carcinoma, FOXP3+TIL and PD-L1+ immune cell infiltration was also significantly higher in CXCL10-positive tumors than in CXCL10-negative tumors (p = 0.019 and p = 0.002, respectively)." (PMID 34504204, 2021). "In invasive carcinoma, infiltration of CD4+, CD8+, and FOXP3+ TIL showed an association with disease-specific survival (p = 0.015, p = 0.039, p = 0.069, respectively) albeit borderline significance for FOX3P3+ TIL." (PMID 33146829, 2021). "When comparing pure DCIS and invasive carcinoma in the whole group, the infiltration of CD4+, CD8+, and FOXP3+ TILs and the presence of PD-L1+ immune cells were significantly higher in invasive carcinoma compared to pure DCIS (all p < 0.001)." (PMID 32216826, 2020). "A thoroughly characterized cohort (n=700) of pure DCIS (n=508) and DCIS with invasive carcinoma, followed for the long term, indicated that high-density tumor-infiltrating lymphocytes (TILs), stromal FOXP3, and PDL1 are poor prognostic factors for DCIS recurrence." (PMID 39555450, 2024). "Furthermore, in combined analyses of S100A8+ IC and other IC subset infiltration, we found that infiltration of S100A8+ IC was associated with decreased disease-specific survival in the PD-L1+ IC (−), CD8+ TIL-low, and FOXP3+ TIL-low subgroups in invasive carcinomas." (PMID 33146829, 2021). "In pre-invasive carcinoma, infiltration of S100A8+ IC revealed weak positive correlations with infiltration of CD4+, CD8+, and FOXP3+ TIL and PD-L1+ IC (rho 0.209–0.281)." (PMID 33146829, 2021). "In invasive carcinoma, CD8+ and FOXP3+TIL infiltration as well as PD-L1+ immune cell infiltration was higher in CXCL10-positive tumors (p = 0.007, p = 0.001, and p = 0.001, respectively)." (PMID 34504204, 2021). "A well characterised DCIS cohort (n = 700) with long-term follow-up comprising pure DCIS (n = 508) and DCIS mixed with invasive carcinoma (IBC; n = 192) were stained immunohistochemically for CD20, CD3, CD4, CD8, FOXP3, PD1 and PDL1." (PMID 32203210, 2020). "In invasive carcinoma, infiltration of S100A8+ IC showed a weak positive correlation with infiltration of CD4+ TIL (rho = 0.263) and a moderate positive correlation with infiltration of CD8+ and FOXP3+ TIL and PD-L1+ IC (rho = 0.474, 0.482 and 0.525, respectively)." (PMID 33146829, 2021). "CD4+, CD8+, and FOXP3+ TIL and PD-L1+ immune cell infiltration was significantly higher in invasive carcinoma compared to pure DCIS regardless of the HR status." (PMID 32216826, 2020).